THBS1 (thrombospondin 1)
Diseases named in the same sentence as THBS1 in open-access papers (continued):
Sharing a sentence is not in itself a finding about the gene and the disease.
atherosclerosis (22 papers, 2010 to 2025). A disease characterized by the build-up of fatty material and calcium deposition in the arterial wall resulting in partial or complete occlusion of the arterial lumen. "It has been suggested that THBS1 plays a role in the pathogenesis of atherosclerosis, where its absence was shown to accelerate atherosclerosis in apolipoprotein E deficient mice." (PMID 35109843, 2022). "Apolipoprotein E (ApoE)-deficient thrombospondin-1 knockout mice displayed increased atherosclerosis compared to Apoe−/− control mice, which the authors attributed to increased metalloproteinase activity and defective efferocytosis." (PMID 31337788, 2019). "Since Tenascin-C and Thrombospondin-1 are associated with sleep bruxism, atherosclerosis, and cardiovascular diseases may be a potential consequence of SB." (PMID 41010873, 2025). "The assay allowed for the measurement of thrombospondin-1 in blood serum samples from patients with atherosclerosis and healthy donors." (PMID 35884911, 2022). "Then, six hub genes (COL1A1, IBSP, CTSD, RAC2, MAF, and THBS1) were obtained through the integration of multisource databases and they were all significantly upregulated in both the osteoporosis and atherosclerosis group compared with the control group." (PMID 35937806, 2022). "The immune-associated genes in both atherosclerosis and osteoporosis from WGCNA mainly included TREM1, CYBB, CCR1, CD83, CD52, IL7R, and THBS1." (PMID 35937806, 2022). "Thrombospondin-1/epidermal growth factor receptor (TSP1/EGFR) signaling is involved in atherosclerosis." (PMID 35001873, 2022). "In this list, two novel biomarker candidates, NPC2 and IGFBP7, were identified along with several proteins, such as THBS1, that have been reported to be involved in atherosclerosis or AA." (PMID 32286426, 2020). "However, few studies directly analyze the role of THBS1 in osteoporosis and atherosclerosis, which emphasizes its importance in future research." (PMID 35937806, 2022). "Short-term stimulation of VSMCs with FGF-2 can cause a transient increase in TSP-1 (Thbs1) expression, which may be one of the ways FGF-2 promotes atherosclerosis." (PMID 35811717, 2022). "Thbs1 is maintained at low levels in the postnatal vessels and elevated in various vascular diseases, including pulmonary arterial hypertension, aortic aneurysms, atherosclerosis, cerebral cavernous malformations and ischemia reperfusion injury." (PMID 35432454, 2022). "Thrombospondin-1 is a member of a family of secreted extracellular matrix proteins that play an important role in cell adhesion, migration and proliferation, angiogenesis, inflammation, atherosclerosis, and thrombosis." (PMID 35884911, 2022). "Consistently high levels of thrombospondin-1, a protein that regulates the interaction of cells with each other and with the extracellular matrix, and vitamin D binding protein, were obtained in patients with atherosclerosis." (PMID 34948066, 2021). "However, recent studies have shown that ApoE-/-/Thbs1 -/- mice treated with exogenous leptin display significant decreases in body weight and attenuation of atherosclerosis." (PMID 33854480, 2021). "Several extracellular matrix molecules, besides PTX3, are able to trap FGF2 in the extracellular environment (such as thrombospondin-1 and cleaved syndecan) and modulate its effects during processes such as inflammation, wound healing, atherosclerosis, and neoplasia." (PMID 29556234, 2018). "Our previous findings highlight a proatherogenic protein, thrombospondin-1 (TSP-1), in hyperglycemia- or hyperleptinemia (mimicking obesity)-induced atherosclerosis." (PMID 36505365, 2022).
oral squamous cell carcinoma (22 papers, 2017 to 2025). "Previous studies have established a significant association between THBS1 and prognosis as well as the tumor microenvironment in patients with oral squamous cell carcinoma (OSCC)." (PMID 37686118, 2023). "M1‐like tumour‐associated macrophages activated by exosome‐transferred THBS1 promote malignant migration in oral squamous cell carcinoma." (PMID 37864310, 2023). "However, multiple independent studies have associated decreased expression of THBS1 with poor prognosis in several cancers, including GC, non‐small cell lung carcinoma and oral squamous cell carcinomas." (PMID 36354023, 2022). "As a tumor-specific ECM protein, THBS1 could promote migration of cancer cells and cause activation of integrin signaling in oral squamous cell carcinoma." (PMID 28410203, 2017). "For instance, Recombinant thrombospondin 1(THBS1) derived from oral squamous cell carcinoma exosomes participates in the polarization of macrophages to an M1-like phenotype through p38, Akt, and SAPK/JNK signaling in the early phase 105." (PMID 40302816, 2025). "In oral squamous cell carcinoma (OSCC), high levels of TAM-derived IL-6, promote EMT and enhance the expression of genes associated with stemness, via the IL-6/STAT3/thrombospondin 1 (THBS1) signaling pathway." (PMID 39981232, 2025). "For example, in oral squamous cell carcinoma, thrombospondin 1 (THBS1) activates the p38, Akt, and SAPK/JNK signaling pathways of TAMs via TAEs and promotes M1 polarization of TAMs, but not M2 polarization." (PMID 39247621, 2024). "Thrombospondin 1 (THBS1), identified as an oncogene in oral squamous cell carcinoma (OSCC), acts as a tumor-specific extracellular matrix (ECM) protein induced by TGFB1." (PMID 38778403, 2024). "M1‐like tumour‐associated macrophages cascade a mesenchymal/stem‐like phenotype of oral squamous cell carcinoma via the IL6/Stat3/THBS1 feedback loop." (PMID 37864310, 2023). "Reports provide evidence that THBS1 derived from oral squamous cell carcinoma (OSCC) exosomes is involved in the polarization of macrophages towards an M1-like phenotype." (PMID 37744272, 2023). "Previously, we have demonstrated that M1-like TAMs activated by exosome-transferred THBS1 promote malignant migration in oral squamous cell carcinoma (OSCC)." (PMID 34991668, 2022). "A previous study showed that THBS1 is the chief tumor-specific ECM protein that froms the tumor microenvironment collaboratively with TGF-β1 to favor oral squamous cell carcinoma invasion." (PMID 33912465, 2021). "In oral squamous cell carcinoma cells, THBS1 upregulated the expression of MMPs and promoted cancer cell migration and invasion." (PMID 34804159, 2021). "For instance, TGFβ1 stimulates THBS1 expression in oral squamous cell carcinoma (OSCC) cells." (PMID 32174791, 2020). "Previously, we demonstrated that exosome-transferred THBS1 polarized macrophages to the M1-like phenotype through p38, Akt, and SAPK/JNK signaling at the early phase in oral squamous cell carcinoma (OSCC)." (PMID 34991668, 2022). "However, expression of THBS-1 was demonstrated to be induced by TGF-β1 in cancer stroma and to promote invasion of oral squamous cell carcinoma." (PMID 32630719, 2020).
colorectal cancer (21 papers, 2015 to 2025). A primary or metastatic malignant neoplasm that affects the colon or rectum. "Here the authors show that bone-marrow derived monocyte-like cells are the primary source of THBS1 in colorectal cancer, associated with mesenchymal characteristics, immunosuppression and a poor prognosis." (PMID 37749092, 2023). "Increased THBS1 is associated with colorectal cancer liver metastasis and THBS1 promotes colorectal cancer cell metastasis by enhancing EMT." (PMID 34804159, 2021). "It has been recently reported that a positive link between high THBS1 expression and mesenchymal characteristics, immunosuppression, and unfavorable colorectal cancer prognosis." (PMID 41019041, 2025). "In the tumor microenvironment, THBS1 has the potential to be utilized as a biomarker for interstitial colorectal cancer detection, and it plays a pivotal role in suppressing anti-tumor immunity." (PMID 39273281, 2024). "There have been several reports that there is a protective role of THBS1 in the anti-angiogenic and anti-tumorigenesis in colorectal cancer." (PMID 34502094, 2021). "As a target of Mir-19a, THBS1 inhibits the survival, migration, and invasion of colorectal cancer cells." (PMID 33712565, 2021). "THBS1 is a potential angiogenesis inhibitor that is frequently methylated in colorectal cancer and malignant glioma." (PMID 26550574, 2015). "In the serum of GC patients, we observed that 63.4% of samples had methylated THBS1, which was slightly higher than previous studies reporting that the methylation frequency in GC and colorectal cancer tissues samples was 48.4% and 44.4%, respectively." (PMID 26550574, 2015). "Activation of XBP1 in TAMs promotes the progression of colorectal cancer, which may be related to the upregulation of SIRPα and THBS1, and the inhibition of macrophage phagocytosis." (PMID 37954130, 2023). "Elevated THBS1 is related to liver metastasis and poor prognosis in colorectal cancer patients." (PMID 37312060, 2023). "THBS1 induces hepatic metastasis by enhancing EMT in colorectal cancer." (PMID 34503278, 2021). "THBS1 was the first member to be identified among the thrombospondin family and has been mostly studied focusing on the development and metastasis in several cancers including colorectal cancer as an anti-angiogenic factor in the tumor microenvironment." (PMID 34502094, 2021). "Multiple SASP-linked proteins that rose in GCR-exposed mouse serum including, PSAP, THBS1, TIMP2, CST3, and PSMA6 are broadly detected in human malignancies, including breast and colorectal cancers were upregulated after GCR exposure." (PMID 41516087, 2025). "It has shown to activate Homo Sapiens Thrombospondin 1 (THBS-1) which is anti-angiogenic in MDA-MB-231 and colorectal cancer HCT-116 cells." (PMID 32630719, 2020). "Notably, genes such as DKK1, GZMB, THBS1, and CCL5—recognized for their key contributions to colorectal cancer prognosis—have been incorporated into several existing prognostic models." (PMID 40670378, 2025).
Stroke (21 papers, 2013 to 2025). Sudden impairment of blood flow to a part of the brain due to occlusion or rupture of an artery to the brain. "In this research, we investigated the association of variations and mRNA expression of THBS1 with the risk of IS and long-term death after stroke." (PMID 36212039, 2022). "In humans, decreases of THBS1 expression by endothelial cells infected with hantavirus is linked to hemorrhagic disease, and elevated serum levels have been seen in stroke patients." (PMID 33668216, 2021). "In later phases of the immune response, hypermethylated promoter of thrombospondin-1 (THBS1), a gene associated with angiogenesis and neuroprotection, decreases stroke recovery." (PMID 33049931, 2020). "Association analyses of THBS1 variants with the risk of long-term death after stroke*." (PMID 36212039, 2022). "In summarizing this study, we affirm that our risk assessment model, based on PADGs, specifically APP, THBS1, F13A1, SRC, PPBP, and VCL, presents robust diagnostic capabilities for stroke patients." (PMID 38268925, 2023). "Lastly, THBS1 gene silencing induced by DNA methylation in post-stroke recovery inhibits neurorestoration, thus exacerbating stroke injury." (PMID 36142283, 2022). "Immunohistochemistry confirmed that THBS1 is expressed in the astroglial scar 2 weeks and 5 weeks after stroke." (PMID 36072905, 2022). "In order to more precisely assess the roles of thrombospondin-1 and thrombospondin-2 and their effects on the prognoses in stroke patients, longer prospective observation following the onset of AIS is needed." (PMID 35268287, 2022). "Specifically, we found that thrombospondin-1 is upregulated in the peri-infarct area after stroke and that pharmacological blockade of thrombospondin receptors by pregabalin improved axon sprouting and functional recovery." (PMID 36072905, 2022). "In diseases such as stroke, THBS1 induces and increases angiogenesis by silencing theTHBS1 expression induced by hypermethylation of the THBS1 promoter region." (PMID 36142283, 2022). "Therefore, this research aimed to investigate whether the genetic variants and mRNA expression of THBS1 was associated with the susceptibility to developing IS and the long-term death after stroke by conducting the case-control and cohort studies in the Chinese population." (PMID 36212039, 2022). "Plasma THBS1 and CFD are confirmed as CHD risk markers, and plasma IGFBP4 and IGFBP2 are confirmed as stroke risk markers." (PMID 24373343, 2013). "The strongest associations in these analyses are for B2M and CHD and for IGFBP4 and stroke, while an inverse association of CHD risk with THBS1 and a positive association of stroke risk with IGFBP2 are also observed." (PMID 24373343, 2013). "B2M, THBS1, and CFD were confirmed (P <0.05) as novel CHD risk markers, and B2M, IGFBP2, and IGFBP4 were confirmed as novel stroke disease risk markers, while the assay for HPX proved to be unreliable." (PMID 24373343, 2013). "Similarly, hypomethylation of TNF receptor-associated factor 3 (TRAF3) and hypermethylation of thrombospondin-1 (THBS1) has also been illustrated to be crucial predictor of stroke-related outcomes." (PMID 36312038, 2022). "RCS regression analyses did not identify significant linear or non-linear correlation between THBS1 mRNA expression and the risk of all-cause death, stroke death, and IS death in IS patients." (PMID 36212039, 2022). "We here found that astrocyte-derived thrombospondin-1 is upregulated in the astroglial peri-infarct scar, and that treatment with the thrombospondin-1 receptor antagonist pregabalin induces axon sprouting and functional recovery after stroke." (PMID 36072905, 2022). "Furthermore, cohort studies did not indicate significant associations between THBS1 variants and the risk of IS incidence or long-term death after stroke." (PMID 36212039, 2022). "In contrast, increased THBS1 expression may terminate the angiogenesis involved in stroke recovery." (PMID 36142283, 2022).
Stroke (continued). "Likewise, the mechanism by which THBS1 contributes to up regulation after stroke in animal models." (PMID 27336623, 2016). "After stroke, CBM neutrophils preferentially increased the expression levels of Cxcl2, Prok2, Ngp, Thbs1, and Cd177." (PMID 39930981, 2025). "Similarly, hypomethylation of TNF receptor-associated factor 3 (TRAF3), hypermethylation of thrombospondin-1 (THBS1), and increased DNA methyltransferase 3A (DNMT3A) activity are indicated as predictors of stroke outcome." (PMID 36855111, 2023). "Similarly, hypomethylation of TNF receptor-associated factor 3 (TRAF3), hypermethylation of thrombospondin-1 (THBS1), and increased DNMT3A activity are indicated as predictors of stroke outcome, as well degree of ischemic injury." (PMID 36855111, 2023). "However, adhesion events were markedly increased following the introduction of arginine-glycine-aspartate (RGD)-labelled synthetic MPs or endogenously-derived EVs from experimental stroke animals carrying excess RGD proteins, including vitronectin, CD40-ligand and thrombospondin-1." (PMID 31676801, 2019).
hepatocellular carcinoma (20 papers, 2006 to 2025). A malignant tumor that arises from hepatocytes. "In hepatocellular carcinoma cells, upregulation of THBS1 promoted cell proliferation and inhibited apoptosis." (PMID 38183097, 2024). "It was shown, however, to be highly expressed in hepatocellular carcinoma and inhibited the transcription of THBS1 by recruiting DNMT3b to its promoter region." (PMID 33274204, 2020). "One study found high THBS1 levels in hepatocellular carcinoma and venous invasion in tumors with low levels of vascular endothelial growth factor (VEGF) protein expression." (PMID 17022822, 2006). "And recently, alteration of the expression of angiogenic genes has been described in hepatoma cells in response to NO donors, in particular an increase in thrombospondin-1 and tissue inhibitors of metalloprotease-1, known inhibitors of angiogenesis and tumor cell migration." (PMID 29568362, 2018). "Several studies reported increased expression of THBS1 in hepatic fibrosis and hepatocellular carcinoma, and a recent review summarizes the function of THBS1 and its activity via CD47 in inhibiting NO, cGMP, cAMP and VEGF signalling to promote thrombosis and to decrease tissue survival." (PMID 29296203, 2017). "Moreover, ephrinA1 affects hepatoma cell growth by regulating the expression of genes related to cell cycle (p21), angiogenesis (angiopoietin 1 and thrombospondin 1), and cell–cell interactions (Rho, integrin, and matrix metalloproteinases) in cultured hepatoma cells." (PMID 33572758, 2021). "M1 macrophages secrete angiostatic factor thrombospondin-1(TSP1) for inhibiting angiogenesis by interacting with an endothelial cell receptor CD36 in various cancers, including hepatocellular carcinoma." (PMID 37965573, 2023). "Thrombospondin-1 (THBS1; upregulated in POAG LC cells) is a major activator of extracellular transforming growth factor beta 1 (TGFβ1) in fibrotic renal disease in the rat and is closely involved in angiogenesis in hepatocellular carcinoma." (PMID 19145252, 2009).